USP17L17 (ubiquitin specific peptidase 17 like family member 17)
Description:
Deubiquitinating enzyme that removes conjugated ubiquitin from specific proteins to regulate different cellular processes that may include cell proliferation, progression through the cell cycle, apoptosis, cell migration, and the cellular response to viral infection.
Tractability: No criterion of Open Targets' tractability assessment is met for any kind of drug.
Gene: Protein-coding gene on chromosome 4 (9,243,879 to 9,245,471, forward strand). Ensembl gene ENSG00000249104.
Subcellular location: Nucleus; Endoplasmic reticulum
Pathways (Reactome):
Metabolism of proteins: Ub-specific processing proteases
Gene Ontology:
Molecular function: cysteine-type deubiquitinase activity
Biological process: regulation of apoptotic process; protein deubiquitination
Cellular component: endoplasmic reticulum; nucleus
Genetic constraint (gnomAD): Missense variants: 0 observed, 0.67 expected, observed/expected ratio (o/e) 0, 90% interval 0 to 1.8.
Homologues: Paralogues in human: USP17L11 (99% identical), USP17L20 (99% identical), USP17L22 (99% identical), USP17L24 (99% identical), USP17L25 (99% identical), USP17L26 (99% identical), USP17L27 (99% identical), USP17L28 (99% identical), USP17L29 (99% identical), USP17L30 (99% identical), USP17L18 (99% identical), USP17L5 (99% identical), and 59 more.